IRS1 (insulin receptor substrate 1)
Diseases named in the same sentence as IRS1 in open-access papers (continued):
Sharing a sentence is not in itself a finding about the gene and the disease.
diabetes (continued). "It was demonstrated that the deletion of both IRS1 and IRS2 genes in the liver of mice (L-DKO mice) prevented activation of hepatic Akt-Foxo1 phosphorylation and resulted in the development of diabetes." (PMID 24497996, 2014). "As a conclusion, we partly revealed pre-diabetes prevention mechanism of TZQ-F, which at least, related to increasing effect on IRS-1-dependent PI3K/AKT signaling pathway in muscle." (PMID 24952587, 2014). "This is the first time to report that the upregulation of insulin signaling proteins (IRS-1 and AKT-2) was obtained in a STZ-induced diabetic rat under ICT by EA." (PMID 21754922, 2011). "Particularly, key proteins of insulin signaling were investigated, i.e., insulin receptor substrate (IRS-1), protein kinase B (PKB/AKT), and glycogen synthase kinase-3 (GSK-3β), which have gained considerable attention from scientists for the treatment of diabetes." (PMID 39795155, 2024). "Studies have shown that animal models lacking IRS1 developed hyperglycaemia, or Type 2 diabetes mellitus; hence, increasing the protein levels of IRS1 will ultimately reduce the hyperglycemia complications." (PMID 38139804, 2023). "Studies have shown that animal models lacking IRS1 developed hyperglycaemia or Type 2 Diabetes Mellitus, hence increasing the protein levels of IRS1 will ultimately reduce the hyperglycaemia complications." (PMID 35956652, 2022). "The Irs1 gene expression was decreased in the diabetes group when compared to the control (P < 0.001), both GQD and metformin can increase the Irs1 expression level which was suppressed by diabetes (P < 0.05)." (PMID 35858880, 2022). "Additionally, we investigated if TRDI elevated insulin signaling in these mice; IRS-1, PDK-1, and Akt were phosphorylated in the STZ-induced diabetes plus TRDI group (G4)." (PMID 35883721, 2022). "Also, a single TRDI dose (G4) increased IRS-1, PDK1, and Akt phosphorylation in diabetic mice when compared with the STZ-induced diabetes control group (G2), supporting our in vitro and in vivo findings." (PMID 35883721, 2022). "The role of tumor protein 63 (TP63) in regulating insulin receptor substrate 1 (IRS-1) and other downstream signal proteins in diabetes has not been characterized." (PMID 33920782, 2021). "Thus, we speculate that IRS1 p.His713Tyr variant causes a defect in binding with PI3K, resulting in a decrease in IRS1-associated PI3K activity and subsequent activation of the kinase Akt and ultimately impairs the insulin message to the cellular vector pathways, thereby causing diabetes." (PMID 32411229, 2020). "Significant elevation of p-IRS-1 in non-diabetes PD patients compared with non-diabetes control was only observed in the p-IRS-1S312 and p-IRS-1S616." (PMID 33344443, 2020). "It has been reported that the absence of IRS-1 or phosphorylated IRS-1 in muscle tissue and adipose tissue is associated with a high risk of diabetes mellitus." (PMID 31355254, 2019). "Once the effects of Axl on glucose uptake and/or glucose metabolism are established, novel strategies may be devised to target the molecules involved in these pathways, e.g., TNS2 and IRS-1, to improve the treatment for PDAC and diabetes." (PMID 30419905, 2018). "The mechanisms of berberine in diabetes and inflammation include: regulating JNK and PPAR-α pathway, influencing transcriptional factors expression, such as PPAR-γ, C/EBP-α, SREBP-1c, LXR, and modulating IRS-1, Akt, and AMPK signal pathway." (PMID 28736524, 2017). "The disruption of IRS1 in mice retards increases in body mass and reduces insulin-stimulated glucose uptake; however, diabetes does not develop because insulin secretion increases in order to compensate for mild resistance to insulin." (PMID 28282409, 2017). "Our meta-analysis showed that PGRMC1, HADH, IRS1 and MPST were the four tissue non-specific genes presenting differential expression association with the diabetes or insulin response." (PMID 28117714, 2017).
diabetes (continued). "Emerging gene-editing technologies, such as CRISPR (clustered regularly interspaced short palindromic repeats)/Cas9 and TALENS (transcription activator-like effector nucleases), will allow deletion or insertion of IRS1, IRS2 or both proteins in vascular cells damaged in diabetes." (PMID 27514532, 2016). "IRS-1 null mice showed growth retardation and mild resistance to insulin, but did not develop diabetes." (PMID 24497996, 2014). "Mice that lack Irs1 display profound growth retardation but do not develop diabetes because insulin secretion compensates for the presence of mild insulin resistance." (PMID 23741292, 2013). "Mice with systemic IRS1 knockouts demonstrate growth retardation, insulin resistance, and beta-cell hyperplasia without diabetes." (PMID 21754917, 2011). "Therefore, the activation of the IRS-1/IRS-2/PI3K/AKT signaling pathway and regulation of its targets, including GLUT4 and GSK-3β, may play important roles in preventing diabetes." (PMID 38799166, 2024). "The mRNA expression levels of PTEN and GSK-3β were significantly increased, while IRS-1, PI3k, Akt, and GLUT-2 were decreased considerably in the DC group compared to the NC group (p < 0.001), demonstrating the dysregulation of the insulin-mediated PI3K/AKT pathway in diabetes." (PMID 38231654, 2023). "Moreover, r-A-FABP treatment impaired the insulin-mediated eNOS pathway in vascular endothelial cells by inhibiting insulin receptor substrate 1 (IRS1) and Akt activation, which implicates the mechanistic linkage between circulating A-FABP and endothelial cell dysfunction in diabetes." (PMID 34502295, 2021). "Gelam honey exerts protective effects against diabetes and hyperglycemia-induced oxidative stress through improving insulin content and insulin resistance by producing the differential expression of insulin signaling pathways MAPK, NF-κB, IRS-1 (ser307) and Akt in HIT-T15 cells." (PMID 33435215, 2021). "In the EA group, we observed a significant increase of IRS-1 protein expression, indicating that EA may induce a plasma glucose-lowering effect in STZ-induced diabetic rats by activating IRS-1 and upregulating GLUT4 translocation from the cytosol to the cell membrane during isoflurane anesthesia." (PMID 34659435, 2021). "Therefore, the neuronal IR/IRS-1 signaling pathway and its downstream PI3K/AKT signaling may play a key role in diabetes-related depression." (PMID 34149862, 2021). "The effect of CPP extract on various genes such as Pdx-1, Ins-1, ngn-3, GLUT-4, and IRS-1 in insulin signaling pathway and Traf-4, Traf-6, and Mapk-8 in MAPK downstream JNK cascade was examined through qRT-PCR to access the core molecular mechanism involved in CPP-induced recovery of diabetes." (PMID 32256963, 2020). "Thus, the mounting evidence do not support the proposed role of MG53 in the regulation of IRS-1 in diabetes." (PMID 33240103, 2020). "Notably, in the context of high-grade serous carcinoma (HGSC) patients, whether they had type 2 diabetes mellitus or not, IRS1 and IRS2 displayed a parallel relationship with each other while exhibiting an inverse relationship with NEDD8." (PMID 38272982, 2024). "The association of Parkinson’s disease with the neural-derived exosomes total and phosphorylated IRS-1 level between PD patients with normal cognition controls (mini-mental state test>26) after the adjustment of age, sex, HbA1c, and body mass index among people without the diagnosis of diabetes." (PMID 33344443, 2020). "We investigated the changes of renal structure and its function in normal glucose tolerance (NGT), impaired glucose tolerance (IGT), diabetes mellitus (DM), and diabetic kidney disease (DKD) stages in OLETF rats and explored the role of the INS/IRS-1/PI3-K/Akt signaling pathway." (PMID 31737684, 2019). "We further investigated the clinical relevance by analyzing the expressions of Insulin, IRS1, IRS2, and NEDD8 in ovarian cancer tissues from patients with or without type 2 diabetes mellitus." (PMID 38272982, 2024).
diabetes (continued). "Also, the lack of insulin in patients with diabetes may contribute to enhanced platelet activation as insulin binds to the insulin receptor (IR) located on the platelet surface and activates insulin receptor substrate 1 (IRS-1) via tyrosine phosphorylation." (PMID 38398275, 2024). "GCG, IRS1, VEGFA, STAT3, CCL2, CASP3, and APOE are the 7 DEPs that are related to diabetes mellitus as specific proteins but not seen among the central proteins of fatty liver disease." (PMID 35154608, 2021).
type 2 diabetes (199 papers, 2004 to 2026). "IRS1 gene polymorphisms Gly972Arg and PPARγ Pro12Ala are 2 types of polymorphisms associated with predisposing to type 2 diabetes but having opposite effects in their effect on adiponectin levels." (PMID 36292779, 2022). "This is in accordance with previous studies that show IRS-1 G972R polymorphism is associated with failure of oral antidiabetic drugs in patients with type 2diabetes." (PMID 36011374, 2022). "Another genetic variation discovered to be associated with type 2 diabetes is genetic variations close to IRS1 (the insulin receptor substrate-1)." (PMID 36292779, 2022). "It has been reported that the A allele of IRS1‐rs10498210 G/A polymorphism induced risk of type 2 diabetes among Iranians." (PMID 35366956, 2022). "Polymorphisms in the INSR and IRS-1 genes associate with type 2 diabetes mellitus (T2DM) and insulin resistance." (PMID 34408667, 2021). "We aimed to investigate the relationship of type 2 diabetes with a Gly972Arg (G972R) variant of the IRS-1 gene and Gly1057Asp (G1057D) polymorphism of IRS-2 gene in the population of Punjab, Pakistan." (PMID 31404179, 2019). "In general, a variety of allele A in IRS1 frequencies have been reported in many studies, and controversial reports have revealed the association of this polymorphism with type 2 diabetes." (PMID 30884193, 2019). "According to the results of this study, the presence of AA genotype in both CCR5 and IRS1 is associated with type 2 diabetes." (PMID 30884193, 2019). "The IRS-1 polymorphisms has been linked to high platelet reactivity in coronary artery disease (CAD) patients with type 2 diabetes mellitus (T2DM)." (PMID 30305144, 2018). "Increased IRS1 ubiquitination and its subsequent degradation have been reported in a mouse model of type 2 diabetes (TALLYHO/Jng mice) and were associated with an increase in SOCS1 levels." (PMID 26965244, 2016). "In adipocytes isolated from obese humans with type 2 diabetes, expression of IRS-1 is reduced, followed by IRS-1–associated PI3K activity decreased, then IRS-2 becomes the main docking protein for PI3K." (PMID 27070590, 2016). "This is indeed the case, as the new version of OMIM links SHORT syndrome to gene PIK3R1, which has a verified in-vitro interaction with IRS1, a gene associated to noninsulin-dependent diabetes." (PMID 26631976, 2015). "rs2943641, located ~500 kb upstream of IRS1, was the first type 2 diabetes risk locus identified in a GWAS that was linked to IR and hyperinsulinemia." (PMID 26090471, 2015). "Searches for abnormalities in IRS‐1 primary structure have identified three polymorphisms that affect 10–15% of patients with type 2 diabetes, but essentially the same prevalence of these substitutions was found in control subjects." (PMID 25472611, 2014). "More importantly, the protein IRS1 (insulin receptor substrate 1) which has a critical role in insulin-signaling pathways and whose mutation is known to result in genetic risk for type 2 diabetes, has been identified as a drug target for cancer." (PMID 23741327, 2013). "Different studies have shown a lower amount of IRS-1 in 30% of subjects at high risk for type 2 diabetes, such as first-degree relatives of type 2 diabetic and obese subjects." (PMID 22442679, 2012). "In this study, we identified a significant association of rs2943641 near IRS1 locus, with type 2 diabetes in the Japanese population." (PMID 22046406, 2011). "Apparently, high-fat diet-induced type 2 diabetes in C57BL/6J mice has defective peripheral glucose utilization due to deficiency in IRS-1, resulting in downstream defect in Akt-1-PI-3 kinase activation." (PMID 21785636, 2011). "In conclusion, these results indicate that the IRS1 locus is considered common locus involved in susceptibility to type 2 diabetes across different ethnic groups." (PMID 22046406, 2011). "A decline of IRS-1 amount or function has been linked to decreased glucose uptake in insulin resistant animal models and type II diabetic patients." (PMID 19787081, 2008).
type 2 diabetes (continued). "Xiao and colleagues proposed that MG53-mediated downregulation of IRS-1 could serve as a causative factor for development of type II diabetes." (PMID 39355613, 2024). "Loss of Irs1 or Akt function results in basal hyperinsulinemia and, in some cases, increased β-cell mass, mimicking the early stages in the progression towards human type 2 diabetes." (PMID 35136059, 2022). "CGA itself does not affect phosphorylation of phosphatidylinositol-3-hydroxykinase (PI3K) and insulin receptor substrate (IRS-1), but metabolites of CGA can cause the phosphorylation of PI3K and IRS-1, thereby enhancing insulin sensitivity and playing a positive role in treating type 2 diabetes." (PMID 35845802, 2022). "The lower of serum miR-126 in type 2 diabetic patients may cause the unbalance of IRS-1 and IRS-2 and therefore promote the pathological injury of β cells." (PMID 26919700, 2016). "The dysregulation of IRS-1 has been implicated in the pathogenesis of type II diabetes and cancer." (PMID 27689988, 2016). "In the present study, we examined 14 SNPs within 13 susceptibility loci for type 2 diabetes in 3 independent Japanese samples, and identified that rs2943641 near IRS1 was significantly associated with type 2 diabetes when we combined the present data with those in the previous Japanese GWAS data." (PMID 22046406, 2011). "Insulin receptor substrate-1 (IRS-1) is a critical element in insulin signaling pathways, and mutations in theIRS-1gene have been reported to have a role in determining susceptibility to traits such as impaired sensitivity to insulin-related to type 2 diabetes." (PMID 36011374, 2022). "Concurrently, at the metabolic level, PKCθ contributes to the pathogenesis of type 2 diabetes by phosphorylating IRS‐1 in skeletal muscle, thereby disrupting the insulin signaling pathway." (PMID 41244006, 2025). "Type 2 diabetes and the mammalian target of rapamycin (mTOR) signaling pathway ranked highest, with IRS1 among the overlapping genes." (PMID 40243885, 2025). "TNF-α, in particular, impairs insulin signaling by promoting serine phosphorylation of IRS-1, while IL-1β exacerbates pancreatic β-cell dysfunction and contributes to the development of type 2 diabetes." (PMID 40867531, 2025). "Meanwhile, in the context of metabolism, PKCθ impairs the insulin signaling pathway in skeletal muscle by phosphorylating IRS‐1, thereby promoting the development of type 2 diabetes." (PMID 41244006, 2025). "As a result, increased serine phosphorylation of IRS-1 reduces insulin-stimulated threonine phosphorylation, leading to insulin resistance and type 2 diabetes (T2D) development." (PMID 39339244, 2024). "ACE2 deficient mice showed increased lipid accumulation in skeletal muscle, while restored endogenous ACE2 in db/db mice (an animal model of type 2 diabetes) improved lipid metabolism through the IKKβ/NF-κB/IRS-1 signaling." (PMID 36902558, 2023). "miR-144 binds to insulin receptor substrate (IRS1) to control its expression and appears to be a potential therapeutic target for type 2 diabetes treatment in humans." (PMID 35498736, 2022). "Among all the polymorphisms studied within the IRS genes, Gly → Arg972 substitution in IRS1, along with environmental factors, appear to have a contributory role in the pathogenesis of type II diabetes." (PMID 35842608, 2022). "The present study aimed to evaluate the role of C. papaya on IRS1 and Akt in high-fat-diet–streptozotocin-induced type 2 diabetic rats and also to analyze the bioactive compounds of C. papaya against IRS-1 and Akt via in silico analysis." (PMID 36235831, 2022). "The likelihood of a positive effect of allele A on the investigated polymorphisms IRS1 -rs10498210 G/A and CCR5-59029 A/G elevates the chance of developing type 2 diabetes." (PMID 36292779, 2022).